MYC (MYC proto-oncogene, bHLH transcription factor)
Diseases named in the same sentence as MYC in open-access papers (continued):
Sharing a sentence is not in itself a finding about the gene and the disease.
tumor (continued). "Finally, we evaluated primary tumor cell samples directly obtained from DLBCL and MM patients using the synthetic MYC inhibitor 10058-F4." (PMID 39596160, 2024). "This research demonstrated that LINC00460 promoted CRC cell immune escape by increasing the expressions of MYC, CD47 and PD-L1 in CRC cells and remodeling the CRC tumor-inhibitory immune microenvironment, thereby promoting the occurrence and development of CRC tumors." (PMID 39135122, 2024). "• Inhibits transcription in tumor cells by targeting genes like RPB1, MYC, SP1 and FOS." (PMID 36969868, 2023). "MCF7 cells (WT, MYC KO, TAF10 KO and DKO) were injected into the flanks of BALB/c nude mice to determine whether these effects translated to a change in tumour growth." (PMID 36639831, 2023). "MYC promotes the secretion of angiogenic factors such as vascular endothelial growth factor (VEGF), which stimulates the growth of blood vessels, ensuring an adequate oxygen and nutrient supply to the tumor." (PMID 37755397, 2023). "MYC is not confined to intracellular activity; it can also extend its influence to the extracellular space by interfering with tumor immunity." (PMID 37755396, 2023). "MYC-driven up-regulation of lncRNA ELFN1-AS1 could silence TPM1 through epigenetic, and further promote tumor growth of CRC." (PMID 37161577, 2023). "In addition, SP1, HIF-1, or MYC modulates the TME, such as the immune system and the production of oncometabolites, in such a way to facilitate tumor development (as discussed in Section 2)." (PMID 37998757, 2023). "In the present review, we describe current knowledge about the interplay between MYC and HIF signaling during neural crest, adrenal development and the potential role of these signaling pathways in catecholamine-producing neural crest-derived neoplasms." (PMID 37361539, 2023). "Another significant result from our preclinical study is that AFP immunization has no efficacy against already-formed c-MYC/Mcl1 tumor lesions due partly to immune escape from AFP-specific T cells." (PMID 37040183, 2023). "Accordingly, in tumor cells, the promoters of all actively transcribed genes are activated by MYC leading to non-linear amplification of pre-existing transcriptional activities." (PMID 36969025, 2023). "To evaluate whether AFP immunization can be effective against AFP(+) HCC, we applied the c-MYC/Mcl1–induced mouse HCC model by hydrodynamic tail vein injection (HDTVi), which exhibited high Afp expression in tumor cells." (PMID 37040183, 2023). "At 20 dpi, the overall tumor volume in the hep-c-MYC/AR-V7 mice was larger than hep-c-MYC mice regardless of the sexes as indicated by increased liver-to-body weight ratio." (PMID 36746917, 2023). "Elsewhere, MYC-amplification has been implicated in immune modulation through the upregulation of the CD47 immune checkpoint protein, which can be expressed on tumour cells as a “do not eat me” signal." (PMID 37232837, 2023). "In our metastatic dataset along with additional primary SCLC patient tumor, circulating tumor cell‐derived xenograft, and patient‐derived xenograft (PDX) datasets, samples overexpressing MYC paralogs (MYC, MYCL, or MYCN) consistently displayed significantly lower CDKN1A expression." (PMID 37491889, 2023). "Moreover, Glycogen Synthase Kinase-3 (GSK-3) mediates a sequence of substrates such as c-MYC and HIF-1α to induce cell growth and tumor development." (PMID 37895941, 2023). "To investigate the mechanism that regulates T-cell infiltration into the Arf1-deficient tumors, we first performed bulk RNA sequence with tumor samples from MYC-ON live tumor mouse models with or without Arf1-knockout." (PMID 39872623, 2023).
tumor (continued). "CJL affected neither the tumor spectrum nor overall tumor burden as revealed by the combined weight of all tumors dissected from each animal in male or female Eμ-MYC mice." (PMID 37811199, 2023). "Furthermore, the highly expressed DEGs of fibroblasts in LNM included immune-related genes (CCL21, CCL19, CCL2, and MYC), metabolism-related genes (STEAP4, FABP4, DPT, and APOE), and genes related to tumor proliferation and progression (RGS, CCN, and MYC)." (PMID 37221625, 2023). "FISH analysis of the tumor tissue from patient 4 showed a gain of MYC in 63.5% of cells, but no amplification as per definition (ratio < 4)." (PMID 37173990, 2023). "The proposed application of such NPs would be to effectively silence the frequently upregulated c-MYC oncogene without side effects or toxicity, resulting in a reduced tumor size." (PMID 37954478, 2023). "Our findings may imply that Ppp2r5d depletion could result in increased c-MYC activation through AKT activation, thus contributing to increased tumorigenesis and tumor progression." (PMID 37627221, 2023). "Where MSC exosomes synthesized by MYC-transformed MSCs, E1-MYC cells were used, no inhibitory or promoting effects were observed on tumor growth." (PMID 37849741, 2023). "The tumor cells expressed CD19, PAX5, CD10, MUM1, and MYC, and showed a proliferation rate of 100%." (PMID 37555980, 2023). "The increase in c-MYC expression by E7 results from the inhibition of Rb and E6 to activate telomerase, and this increase in c-MYC expression will eventually be effective in tumor progression." (PMID 36843070, 2023). "10058-F4 treatment reduced MYC and HIF1A-As2 expression in tumor." (PMID 37041291, 2023). "Here, we show that BCL-W appears dispensable for MYC-driven lymphomagenesis, and such tumours arising in the absence of BCL-W show no compensatory changes to BCL-2 family member expression, nor altered sensitivity to BH3-mimetic drugs." (PMID 37567974, 2023). "In conclusion, our work uncovers the phospholipid transporter PITPNC1 as a KRAS effector that controls central transcriptional and signalling nodes (i.e. MYC and mTOR) and unveils novel therapeutic strategies for KRAS-driven tumours in the context of a PITPNC1-regulated transcriptional network." (PMID 37210549, 2023). "Before overt tumor nodules appeared in our HCC model, preneoplastic cells could be identified by their high MYC expression, reflecting successful transfection and oncogene expression." (PMID 37640929, 2023). "Moreover, the TUG1 lncRNA was found to sponge miR-145, which is a reported tumor suppressor that helps regulate SOX2 and MYC mRNA levels and thus upregulates the abundance of these key stemness-associated TFs in glioma." (PMID 37444543, 2023). "As a responsive gene of c-MYC and E2F1, CDCA7 participates in tumor transformation." (PMID 37510310, 2023). "MYC gene expression is tightly regulated by PI3K and BRD4, therefore concomitant inhibition of PI3K and BRD4 blocks MYC expression and activation, leading to decreased tumor growth and metastasis." (PMID 37142850, 2023). "Recent studies have demonstrated the effectiveness of re-engineering FDA-approved tricyclic neuroleptics, particularly small-molecule activators of PP2A (SMAPs), in inducing apoptosis, promoting the dephosphorylation of PP2A targets such as MYC and AKT and suppressing tumor growth in mouse models." (PMID 37755397, 2023).
tumor (continued). "The tumor cells were negative for MYC and BCL2 rearrangements but positive for BCL6 rearrangement by fluorescent in situ hybridization." (PMID 37884941, 2023). "To determine the effect of CTDNEP1 deficiency on tumor cell growth, we inhibited CTDNEP1 expression in different G3-MB tumor cells with or without MYC amplification using lentiviral shRNAs." (PMID 36765089, 2023). "Furthermore, it inhibits MYC/MAX interaction and induces apoptosis in tumor tissue derived from a MYC-driven xenograft tumor model." (PMID 36969025, 2023). "To further our understanding of this mechanism, we found significantly less nuclear c-MYC in tumor tissue derived from Sirt2−/− HCC mice, suggesting that c-MYC is targeted for degradation prior to entering the nuclear compartment where it functions as a transcription factor." (PMID 37628798, 2023). "We did not detect increased levels of MYC or Ki-67 expression in our RNA-seq data nor did we detect elevated numbers of T cells after nearly 3 weeks of in vivo surveillance in tumor-bearing mice." (PMID 37945901, 2023). "While our data in orthotopic PDX confirmed the effectivity of class I HDACi in MYC-amplified MB, we did not observe an anti-tumor effect of volasertib alone, nor a synergistic effect on tumor size or survival in the combination." (PMID 37183219, 2023). "We find that JQ1 suppresses MYC transcription and can synergize with CHEK1 inhibitor prexasertib to suppress tumor growth more effectively than either single agent alone, while prolonging survival in the animals bearing CTDNEP1-deficient MYC-amplified MB tumors." (PMID 36765089, 2023). "Furthermore, combined expression of MYC/PIK3CAE545K and MEK1DD or ER-KRASG12V in not only late-passage but also early-passage HCK1T/16epi cells gave rise to highly potent tumor-initiating cells." (PMID 36763589, 2023). "Compared with Cluster1, Cluster2, with poorer prognosis, had chromosomal amplification of various tumor-promoting gene loci, such as E2F3, MYC, and GATA3, and partial or complete deletion of the chromosome where the tumor suppressor gene PTEN and RB1 loci are located." (PMID 37767092, 2023). "It was also observed that two patients had copy number gains of 8q24.21 (MYC) in plasma samples, and three patients had this amplification in metastatic tissue samples, of which one patient was found with TNBC on one side of primary tumor." (PMID 37293877, 2023). "Activation of the signal integrator GCN2 facilitates tumor cells escape from MYC-driven apoptosis via an MYC/GCN2/eIF2α negative feedback loop." (PMID 36755301, 2023). "Recently, a new model with c-MYC overexpression has been reported (Dbh-iCre/CAG-C-MYC mice); however, the details on the tumor frequency and disease phenotype are not yet available." (PMID 37444423, 2023). "To evaluate the effect of c-MYC overexpression in this mouse model, we first studied B cell development in the bone marrow (BM) of young, pre-tumor stage λ-MYC mice, defined as mice that do not show tumoral masses or signs of disease." (PMID 37809061, 2023).
tumor (continued). "Quantification of MYC intensities in tumor cells and densities of immune cell types in consecutive slides revealed a significant negative correlation between MYC expression and infiltration of CD3+, CD4+, FOXP3+, pSTAT1+, and MHCII+ immune cells." (PMID 37642941, 2023). "Consistent with a previous report, anti–PD-L1 monotherapy demonstrated no survival benefit in the c-MYC-induced HCC tumor model." (PMID 37040183, 2023). "Moreover, miR-644a simultaneously inhibits the expression of MYC, AKT, IGF1R, and GAPDH, which in turn inhibits the Warburg effect in tumor cells and increases the Enz sensitivity of CRPC." (PMID 37370750, 2023). "In this process,MYC could be a direct transcriptional target responsible for YAP-induced tumorigenesis, blockade of which could efficiently rescue such tumor initiation." (PMID 36924251, 2023). "MYC overexpression in tumor cells causes a decrease in the formation of MAX/MAX homodimers, which, in normal conditions, attenuate the binding of MYC to specific (E-boxes) and non-specific DNA sequences." (PMID 36830948, 2023). "Genetic disruption of the c-MYC–WDR5 interaction in a Burkitt lymphoma cancer context results in impaired tumorigenesis and tumor regression revealing the importance of the MYC–WDR5 interaction to tumor function and implicating WDR5 as an essential MYC interaction partner." (PMID 37336886, 2023). "Enhancers at the loci of oncogenes, such as MYC and HRAS, play a critical role in pancreatic ductal adenocarcinoma cell transition into squamous cells, cell migration and invasion in vitro, and accelerated tumor growth and metastases in vivo." (PMID 38135679, 2023). "Patient 1’s PDX tumor was resistant to all treatments except P/CQ, further suggesting that P/CQ treatment is effective against T/HCQ-resistant PDAC with elevated c-MYC expression." (PMID 36719686, 2023). "As seen, a modulator possessing the activities on uPAR and MYC, an oncogene, could be prone to affecting cell proliferation and survival, whereas one possessing the activities on uPAR and SMAD4, a tumor suppressor gene, could affect angiogenesis and migration." (PMID 37895906, 2023). "The rare tumor cell that exhibited moderate nuclear RUNX3 expression coincided with very weak or no discernible MYC protein expression." (PMID 37400551, 2023). "In contrast, non-steatohepatitic tumor foci were not developed in female c-MYC/AR-FL mice and relative surface tumor area was not obviously different from that of female hep-c-MYC mice." (PMID 36746917, 2023). "Researchers found that Nav1.5 knockdown could inhibit the expression of β-catenin, cyclin D1, and MYC in the WNT/β-catenin signaling pathway, thus promoting the apoptosis of tumor cells and effectively inhibiting the migration and invasiveness of tumor cells." (PMID 36966168, 2023). "HIF1A-As2 KD by ASO significant repressed MYC, and mesenchymal markers TFAP4 and SNAIL in tumor." (PMID 37041291, 2023). "For example, in bladder cancer, METTL3 is significantly overexpressed and is associated with proliferation, invasion, and tumorigenic capacity in in vivo, and METTL3 promotes tumor progression through m6A modification on AFF4 and NF-κB mRNA, which in turn activates MYC transcription." (PMID 36830614, 2023). "We and others have also shown that MYC(N) promotes FA biosynthesis and aberrant activation of SREBP118 in cancer, including NB22,23, and genetic and pharmacological interference with FA biosynthesis blocks MYC-driven tumor growth." (PMID 35764645, 2022).
tumor (continued). "These tumours rely on ATR, CHK1 and also USP1 activity for their survival, suggesting that targeting USP1 would be an alternative strategy for treating cancers with high levels of MYC-induced replication stress." (PMID 36240066, 2022). "However, it is intriguing to note that intracellular expression of c-MYC, a recognised proto-oncogene located downstream of TLR7 and TLR9, can modify tumour cell sensitivity to Irofulven." (PMID 35801728, 2022). "In tumor cells, SEs at the MYC locus are looped to a common CTCF site within the MYC promoter." (PMID 35740532, 2022). "Databases indicate that there is a higher expression of c-MYC in HCC44 cells than in H358 cells, which we could confirm on protein level in our 3D tumor model." (PMID 35565305, 2022). "Importantly, a short interval treatment of CpG/aOX40 significantly reduced the fraction of immunosuppressive Tregs within mouse MYC-driven TNBC tumors and increased both numbers and functionality of tumor infiltrating cytotoxic CD8 + T cells." (PMID 35760778, 2022). "We also did not observe a compensation of c-MYC when targeting HIF-1α through USP25, which has previously been linked to HIF activity and shown to be upregulated in a PDAC initiation tumor model with HIF1A deletion." (PMID 35440539, 2022). "The molecular mechanisms accounting for increased MYC and PVT1 expression in most tumor samples in our study are currently unknown, and this line of work will be addressed in future studies." (PMID 36139061, 2022). "In the case of MYC and MET, it is tempting to speculate that MYC superimposes molecular traits over those otherwise present in MET tumours." (PMID 36433941, 2022). "To test the association of MYC, SUMOylation, and the MHC-I pathway, we compared primary tumor samples with MYC amplification against samples without MYC amplification." (PMID 35499080, 2022). "A CSRS scoring system including four CS genes (MYC, DLX2, EPHA3, and LIMK1) was constructed, which could distinguish the survival outcome, tumor microenvironment (TME) status, and ICB treatment response of patients with different CSRS score." (PMID 36106335, 2022). "Direct control of MYC expression in tumor cells without exuberant stress on healthy tissues remains an unsolved task." (PMID 35563017, 2022). "The canonical pathway for miR-21-induced oncogenesis is through to be the direct repression of various well-known tumor suppressor genes, including PTEN and PDCD4, which activate cyclin-dependent kinases, c-MYC, and PI3K/AKT/mTOR pathways, which results in an increased invasion and metastasis." (PMID 35216281, 2022). "Furthermore, mir-17 and 20a positively correlate with MYC and MIR17HG, and, conversely, negatively correlated with FOXA1 in overall primary tumor samples." (PMID 36550153, 2022). "In addition, targeting MUC1-C with a MUC1sgRNA, which suppressed MYC and NOTCH2 in vitro, resulted in complete inhibition of tumor growth." (PMID 35612556, 2022). "As MYC is often overexpressed in PDAC and has central roles in tumor maintenance, MYC may have utility either as a therapeutic target to improve therapeutic responses or a potential biomarker for PARP inhibitor sensitivity in PDAC tumors." (PMID 35205643, 2022). "This tumor growth was significantly larger and more accelerated when compared with nude mice harboring cell lines that lacked c-MYC stabilization." (PMID 36439412, 2022). "MYC and CCND1 are well known WNT-induced genes that promote cell proliferation and tumor growth." (PMID 35908024, 2022). "The scarcity of tumor cells in tumor biopsies did not enable the performance of molecular analysis, especially to investigate MYC, BCL2, or BCL6 rearrangement." (PMID 35538643, 2022). "Most of the key glycolytic enzymes are affected by MYC and HIF-1α in tumor glycolysis metabolism." (PMID 36532721, 2022).